BRCA1 (BRCA1 DNA repair associated)
Diseases named in the same sentence as BRCA1 in open-access papers (continued):
Sharing a sentence is not in itself a finding about the gene and the disease.
breast cancer (continued). "HCC1937 breast cancer cells, that harbor a 5382insC germ-line mutation of BRCA1, were demonstrated to have a significant accumulation of various types of DNA damage and chromatid breaks after ionizing radiation compared to MCF7 cells that are BRCA1 hemizygous." (PMID 24704793, 2014). "We previously reported that women from high-risk families who tested negative for a BRCA1 or BRCA2 (BRCA1/2) mutation were four times more likely to develop breast cancer compared to women in the general population." (PMID 24667084, 2014). "Our findings imply that genetic (e.g., BRCA1 mutation) and epigenetic mechanisms (e.g., DNA methylation and histone modifications) are jointly involved in the malignant progression of PEMT-related breast cancer." (PMID 24675476, 2014). "In this study we demonstrated in vitro that a mechanism involving the microRNA miR-342 and the two genes ID4 and BRCA1, which are frequently altered in breast cancer, could have a role in the pathogenesis of this tumor type." (PMID 24475217, 2014). "BRCA1 mutation carriers have an 85% risk of developing breast cancer but the risk of developing non-hereditary breast cancer is difficult to assess." (PMID 25067956, 2014). "Both the BRCA1 and the BRCA2 promoter are bound and activated by ETS transcription factors: GA-binding protein α/β (GABPα/β) binds the RIBS element in the BRCA1 core promoter, and overexpression of GABPα/β in breast cancer cells was able to stimulate BRCA1 promoter activation." (PMID 24624361, 2014). "The study has demonstrated that BRCC3 depletion prevents the formation of BRCA1 nuclear foci, and subsequently impairs the DNA repair pathway in response to DNA damage by ionizing radiation in breast cancer cells, suggesting that BRCC3 is referred as a potential therapeutic target for breast cancer." (PMID 25337721, 2014). "In summary, the prevalence of 17q25.3 gain did not exceed 17.2% in unscreened and non-mutated breast cancers (17/99), while the gain was observed in more than 90% of the BRCA1-mutated tumors (29/32)." (PMID 25416589, 2014). "ID4 is expressed in breast cancer and can negatively regulate BRCA1 expression." (PMID 24475217, 2014). "SIRT1 mRNA and protein levels were significantly lower in cell lines derived from mammary tumors lacking BRCA1 compared with cell lines derived from tumors without BRCA1 mutation." (PMID 25486244, 2014). "Breast cancers carrying BRCA1/2 germline mutations often occur in younger women, and present a lack of ER/PR expression (mostly among BRCA1-positive tumours)." (PMID 24944648, 2014). "The goal of this pilot study was to develop and evaluate a protocol for telephone communication of clinical BRCA1/2 (breast cancer) genetic test results that might be broadly generalizable." (PMID 25355401, 2014). "The known high risk susceptibility genes for breast cancer, e.g. BRCA1, BRCA2, ATM, and PALB2, are responsible for approximately 20% of the hereditary cases, but several unknown breast cancer–predisposing genetic factors still exist." (PMID 25029565, 2014). "Importantly, we have found a strong correlation between the expression level of BRCA1 in breast cancer cases and its methylation levels detected by the Methyl II Signature PCR Array." (PMID 25403427, 2014). "Preventive measures and risk factors for breast cancer development in these high-risk women have not been evaluated to the same extent as BRCA1/2 positive women." (PMID 24667084, 2014). "Additionally inherited mutations of BRCA1 and BRCA2 (breast cancer 1/2) are associated with patients who have hereditary breast cancer, accounting for 5–10% of all breast cancer patients." (PMID 25207935, 2014). "In another study, 399 women, from 356 non-BRCA1/2 breast cancer families (some had more than one index case because multiple women were affected at the same age), were screened for FANCD2 mutations by DHPLC/sequencing and no pathogenic mutations were identified." (PMID 25093046, 2014).
breast cancer (continued). "Then, the consensus E2F1 (con.E2F1) and mutated E2F1 (mut.E2F1) were transiently transfected into 293 T cells, and primary non-mutated and BRCA1-mutated breast cancer and their corresponding normal breast cells." (PMID 24502362, 2014). "The BD-L signature correlates with breast cancer cell line pharmacologic response to a combination of poly (ADP-ribose) polymerase (PARP) inhibitor and temozolomide, and the signature outperformed four published gene signatures of BRCA1/2 deficiency." (PMID 24625110, 2014). "Elevated HRD scores were highly associated with BRCA1/2 deficiency regardless of breast cancer subtype, and the most robust predictor of HRD deficiency is likely to be a combination of all three individual HRD scores." (PMID 25475740, 2014). "Despite intense research, GWAS and next generation sequencing (NGS) exome studies have not identified additional major breast cancer susceptibility genes, such as BRCA1 and BRCA2." (PMID 25360583, 2014). "However, in our cohort, only 6.0% of the TMBC patients had a family history of breast cancer, indicating that the correlation between TMBC and the BRCA1 mutation remains to be determined." (PMID 25375803, 2014). "To get a comprehensive approach of the role of BRCA1 in tumor cell metabolism, we performed a global transcriptional and metabolite profiling in a BRCA1-mutated breast cancer cell line transfected or not by wild-type BRCA1." (PMID 25010005, 2014). "To investigate the epigenetic regulation of PEMT, we compared the DNA methylation patterns of three promoters between BRCA1-mutated or non-mutated breast cancer and their adjacent normal breast tissues." (PMID 24675476, 2014). "The results showed that women with deleterious BRCA1 mutations who breast-fed for a cumulative total of more than one year, presented a statistically significantly reduced risk of breast cancer than those who did not breast-feed their children." (PMID 24763114, 2014). "Research indicated that lowering the level of BRCA1 mRNA could increase carboplatin sensitivity in breast cancer cell lines and lead to antimicrotubule drug resistance." (PMID 24591771, 2014). "However, it’s widely accepted that hereditary transmission of some predisposition genes, especially BRCA1 and BRCA2, are the most known factors to be directly involved in the pathogenesis of breast cancer and is associated with 5–10% of breast cancer cases." (PMID 25926863, 2014). "One familial breast cancer patient showed an ambiguous deletion in exon 6 of BRCA1 gene." (PMID 24906410, 2014). "Neither a family history of breast cancer nor the presence of a pathogenic mutation in BRCA1/2 genes were associated with an increased micronuclei frequency." (PMID 25415331, 2014). "Genetic mutations in BRCA1 and BRCA2 account for approximately 20% of breast cancer cases." (PMID 25360583, 2014). "Several other studies have also described cases of patients with MEN1 and a family history of breast cancer, however, in these studies, the breast cancer was caused by mutations of the BRCA1/2 gene not the MEN1 gene." (PMID 24959251, 2014). "Using an in vitro assay, it was found that both missense SNPs in this breast cancer were mild alleles that partially reduced, but did not eliminate, BRCA1 protein function." (PMID 25390934, 2014). "Patients with positive BRCA1 mutation experienced more bilateral breast cancers than non-carriers [6 (15.8%) vs. 2 (2.6%), respectively]." (PMID 24348864, 2014). "The HRD scores showed strong correlation with BRCA1/2 deficiency regardless of breast cancer subtype." (PMID 25475740, 2014). "Also, BRCA mutations are more frequent in high-grade serous ovarian cancers and in basal-like breast cancers in the case of BRCA1." (PMID 25226589, 2014).
breast cancer (continued). "Interestingly, the genetic background used for screening was the Brca1/Trp-53 which in the majority of cases gives rise to ER- mammary tumours of high grade." (PMID 24559095, 2014). "In breast cancer, PTEN loss is more prevalent in association with BRCA1 germ-line mutations, and tumour analysis at the single-cell level has shown that it is the most common initiating event in BRCA1-associated breast tumours." (PMID 25608477, 2014). "Due to the extremely complex regulation of BRCA1 subcellular localization, it is not surprising that a plethora of mutations were characterized from breast cancer patients resulting in either the loss or gain of BRCA1 function." (PMID 24429466, 2014). "Here, the authors show that cells heterozygous for several BRCA1 mutations are universally defective in the response to replication stress, which could contribute to the BRCA1 breast cancer development pathway." (PMID 25400221, 2014). "Indeed, we have shown significant epigenetic changes in 9 different breast cancer-related genes, other than BRCA1, in WBC from both the carriers and breast cancer patients." (PMID 25403427, 2014). "Our results could provide an alternative approach to finding effective therapeutic ruthenium-based agents with promising anticancer activity, and demonstrated that the BRCA1 RING domain protein was a promising therapeutic target for breast cancers." (PMID 24507701, 2014). "Interestingly, the proportion of ER-negative breast cancers among BRCA1-likeCGH and BRCA2-likeCGH breast cancers was similar to that reported for BRCA1-mutated and BRCA2-mutated breast cancers, respectively." (PMID 24887359, 2014). "There is an overlap between BRCA1-associated cancers, TNBC and basal-like breast cancer." (PMID 24348864, 2014). "BRCA1 is an important breast cancer tumor suppressor gene that functions in DNA damage responses." (PMID 25400658, 2014). "Only 6% of our index patients had serous carcinoma and breast cancer, and no BRCA1/2 mutations were found in families that fulfilled the testing criteria for HBOC." (PMID 24851142, 2014). "Our results could provide an alternative approach to finding effective therapeutic ruthenium-based agents with promising anticancer activity, and have identified the BRCA1 RING domain protein as a promising therapeutic target for breast cancers." (PMID 24507701, 2014). "LOH at BRCA1 locus was investigated in two tumors, one breast carcinoma and the MMMT." (PMID 24516540, 2014). "Triple-negative and basal-like breast cancers are often associated with high proliferation, high grade, young age (<38 years), lack of BRCA1 protein expression and aggressive clinical behavior (lymph node and distant metastases occurrence)." (PMID 25369070, 2014). "In this study, we hypothesized that if constitutional BRCA1 methylation reflects an elevated risk for developing breast cancer (BC), WBC that harbor methylated BRCA1 in both cancer-free females and BC patients should exhibit similar molecular changes." (PMID 25403427, 2014). "Four transcription factors (Bcl11a, Grhl3, Prox1, Sox11) activated in Brca1-/- mouse tumors and basal-like human breast cancers across multiple datasets were chosen for validation studies, and all were confirmed to be embryonic-enriched and highly expressed by some tumors." (PMID 23506684, 2013). "Consistent with this, the morphological and immunohistochemical phenotype of BRCA1 mutation-related breast cancer is also different from that of non-BRCA mutation-related breast." (PMID 23409121, 2013). "Moreover, BRCA1 blocked the expression of two endogenous estrogen-regulated gene products in human breast cancer cells." (PMID 23533376, 2013).
breast cancer (continued). "Despite the fact that women who inherited mutations in the BRCA1 and BRCA2 genes have a high risk of developing breast cancer, studies have also shown that significant exposure to certain metal compounds and organic solvents also increases the risks of mammary gland carcinogenesis." (PMID 23762568, 2013). "One patient with ovarian cancer (negative BRCA1/2 mutation) diagnosed at age 47 had multiple family members with breast cancer at a young age (42 and 48 years old), leukemia (20 years old), brain tumor and other malignancies." (PMID 23670029, 2013). "BRCA1 mutated breast cancers are usually estrogen-receptor negative and have a basal phenotype, while BRCA2 mutated tumours exhibit a broader spectrum of phenotypes." (PMID 24025454, 2013). "First, the familial breast-ovarian cancer either due to heterozygous germline mutations in BRCA1 (OMIM #604370) or BRCA2 (OMIM #612555), because the index patient and her sister had early-age-onset (≤50 years) breast cancer and the index patient bilateral disease." (PMID 24373500, 2013). "Even considering the intrinsic limitations of exome resequencing studies, our findings support the hypothesis that the majority of non-BRCA1/BRCA2 breast cancer families might be explained by the action of moderate and/or low penetrance susceptibility alleles." (PMID 23409019, 2013). "BRCA1 may also be a potential regulator of the insulin-like growth factor 1 receptor in human breast cancer cell line HCC1937." (PMID 24321281, 2013). "In the French-Canadian population no mutations were detected in 25 (0%) BRCA1/2-negative familial breast cancer patients." (PMID 23806170, 2013). "A possible explanation could be that ER+ breast cancers in BRCA1 carriers may be incident and sporadic in nature (phenocopies) and not directly caused by the BRCA1 inactivation." (PMID 23704984, 2013). "The goal of this study was to determine the prevalence of PALB2 mutations in a population of BRCA1/BRCA2 negative breast cancer patients selected from either a personal or family history of pancreatic cancer." (PMID 23935836, 2013). "We screened for RAD51D mutations in BRCA1/2 mutation-negative index cases from 1,060 familial breast and/or ovarian cancer families (including 741 affected by breast cancer only) and in 245 unselected ovarian cancer cases." (PMID 23372765, 2013). "Initial reports of comprehensive screening of all of the protein encoding exons of PALB2, identified no variants in 38 breast cancer families, where 22 families had a prior probability of greater than 10% of harboring a BRCA1 or BRCA2 mutation." (PMID 23302520, 2013). "Not everyone with a BRCA1 mutation develops cancer, but the risk is significantly increased (up to 87% lifetime risk of breast cancer)." (PMID 25032017, 2013). "Patient clinical characteristics and BRCA1 promoter methylation in early-stage breast cancer." (PMID 23405268, 2013). "The PARP inhibitor, AZD2281 (Olaparib) given to patients with BRCA1- and/or BRCA2-deficient advanced breast cancer (of which >50% were triple-negative) in a single arm study resulted in an overall response rate of 41% and progression free survival of about six months." (PMID 23717600, 2013). "Reports about ASE of both BRCA1 and BRCA2 to be associated with increased breast cancer risk indicated that in some of the cases, ASE could be explained by mutations activating the nonsense mediated mRNA decay." (PMID 23383130, 2013). "Carriers of BRCA1 mutations develop particular types of breast cancer, specifically estrogen receptor negative (ER−ve) tumours that are often classified as belonging to one of a few special histological types." (PMID 23341493, 2013).
breast cancer (continued). "Similar correlations were also observed in postmenopausal females, females with a family history of breast cancer and females without BRCA1/2 mutations." (PMID 24137204, 2013). "The silencing of the BRCA1 gene by promoter DNA hypermethylation occurs in breast cancer (13%), but depending on cancer subtypes, BRCA1 promoter hypermethylation is present in 55% of sporadic mucinous breast carcinomas and in 67% of medullary breast carcinomas." (PMID 23873296, 2013). "Our previous study had shown that early onset African-American and Hispanic/Latina breast cancer patients did not express increased frequency of BRCA1 mutations, in particular the BRCA1 185AG deletion." (PMID 24167614, 2013). "Despite germ-line mutations in BRCA1 can account for a significant fraction of familial breast cancer cases, a large proportion of familial breast cancer are not related to mutations in BRCA1 or BRCA2." (PMID 23405268, 2013). "Therefore, new methods are needed to aid in the interpretation of uncertain variants as well as to increase the detection rate of BRCA1 and BRCA2 germline mutations for genetic counseling and clinical management of familial breast cancers." (PMID 23704984, 2013). "A comprehensive analysis of the PARP-1/BRCA1/53BP1 factors of DNA repair in the different breast cancer subtypes could enable this selection and promote the use of these compounds outside the TN subtype." (PMID 24191908, 2013). "With immunofluorescence staining and confocal microscopy, we were able to detect BRCA1 sub-nuclear localization in frozen breast cancer tissue specimens and co-localization of BRCA1 and nucleolin in MCF7 (hemizygous for BRCA1 wild type), and HCC1937 (BRCA1 5382insC) cells." (PMID 23855721, 2013). "Therefore, the potential factor(s) contributing the effectiveness of PARP inhibitors in the cytotoxicity of breast cancer cells with mutant BRCA1 needs to be explored." (PMID 23388117, 2013). "In addition to BRCA1 and BRCA2, other breast cancer susceptibility genes have also been extensively studied in Chinese." (PMID 23318652, 2013). "The Kaplan-Meier survival curves of the early-stage breast cancer patients plotted into 2 groups according methylation of BRCA1 promoter region showed that patients with methylated BRCA1 promoter had a significantly shorter OS and DFS than patients with unmethylated gene." (PMID 23405268, 2013). "However, the pathogenic mutations found in BRCA1/2 genes account for only ~40% of familial breast cancer cases and there is a wide cohort of subjects harboring wild-type BRCA1/2 genes." (PMID 24179442, 2013). "However, the occurrence of the c.687delT mutation in other populations has been difficult to confirm among non-BRCA1/2 hereditary breast cancer patients from the UK and France." (PMID 24079363, 2013). "Our group found that ERα, PR, and BRCA1 mRNA levels could be used to better identify those postmenopausal breast cancer patients who will respond the best to AI therapy." (PMID 24223121, 2013). "However BRCA1 and BRCA2 have been associated with mammary tumours in English springer spaniels in Sweden." (PMID 23738139, 2013). "In conclusion, this study highlights the frequent promoter methylation of BRCA1 and its prognostic significance, irrespective of BRCA1 gene mutation in Taiwanese patients with early-stage breast cancer." (PMID 23405268, 2013). "BRCA1 and BRCA2 variations found to affect kinase binding to these sites will be invaluable in the prioritization for further functional characterization and/or association studies in breast cancer." (PMID 23704879, 2013).